VWA5A (von Willebrand factor A domain containing 5A)
Description:
May play a role in tumorigenesis as a tumor suppressor. Altered expression of this protein and disruption of the molecular pathway it is involved in, may contribute directly to or modify tumorigenesis.
Synonyms: BCSC-1; BCSC1; LOH11CR2A
Tractability: PROTAC: ubiquitination databases record sites on it; its protein half-life has been measured.
Gene: Protein-coding gene on chromosome 11 (124,115,404 to 124,147,721, forward strand). Ensembl gene ENSG00000110002.
Subcellular location (Human Protein Atlas): Nucleoplasm; Nucleoli
Gene Ontology:
Molecular function: protein binding
Cellular component: nucleoplasm
Genetic constraint (gnomAD): Loss-of-function variants: 72 observed, 82.42 expected, observed/expected ratio (o/e) 0.87, 90% interval 0.72 to 1.06. The upper end of that interval is the gene's LOEUF score, 1.06, which puts it in group 4 of 6, group 1 being the genes least tolerant of losing a copy. Missense variants: 955 observed, 982.72 expected, observed/expected ratio (o/e) 0.97, 90% interval 0.92 to 1.02. Synonymous variants: 327 observed, 355.67 expected, observed/expected ratio (o/e) 0.92, 90% interval 0.84 to 1.01.
Homologues: Orthologues: chimpanzee VWA5A (99% identical), macaque VWA5A (91% identical), pig VWA5A (73% identical), dog VWA5A (72% identical), guinea pig VWA5A (70% identical), mouse Vwa5a (69% identical), rat Vwa5a (67% identical), mouse AW551984 (66% identical), rat Vwa5al1 (62% identical). Paralogues in human: VWA5B1 (29% identical), VWA5B2 (25% identical), PARP4 (19% identical), ITIH3 (17% identical), ITIH4 (17% identical), ITIH1 (17% identical), ITIH6 (16% identical), ITIH2 (15% identical), VWA3A (15% identical), ITIH5 (14% identical), VWA3B (14% identical).
Diseases named in the same sentence as VWA5A in open-access papers:
VWA5A is named in the same sentence as 14 diseases in open-access papers, as found by Europe PMC text mining. Sharing a sentence is not in itself a finding about the gene and the disease. The quoted sentences say what the papers report.
breast carcinoma (4 papers, 2011 to 2024). "Via Cancer Target Gene Screening (CTGS), we sought to assess the prognostic significance of VWA5A expression in the Molecular Taxonomy of Breast Cancer International Consortium (METABRIC) dataset." (PMID 38291227, 2024). "We found that both Aw551984/VWA5A were negatively regulated by Mta1 in MEFs and human breast cancer cells." (PMID 21364872, 2011).
colon cancer (2 papers, 2018 to 2021). "This differential behavior of M5-T1 compared with F4-T2 and F5-T1 was also observed for FIBB, CD44, and VWA5A, in agreement with the fact that both CD44 and VWA5A were interesting markers for detection of the early stages of colon cancer in the plasma." (PMID 29662647, 2018). "Five genes (FAS, VWA5A, SPTBN2, PCK1, and TIMP1) significantly affect the prognosis of patients with colon cancer." (PMID 34957118, 2021). "Finally, the ARGPI was constructed based on five apoptosis genes (FAS, VWA5A, SPTBN2, PCK1, and TIMP1), which can effectively improve the prediction of colon cancer progression." (PMID 34957118, 2021).
asthma (1 paper, 2020). "Notably, LINC02145 exhibited to be correlated to six asthma-related genes, including ZFN19, G2E3, ATF7IP, PEA15, SPDYE6, VWA5A." (PMID 32948203, 2020).
breast tumour (1 paper, 2015). "For instance VWA5A encodes the von Willebrand factor A domain containing 5A, a known breast tumour suppressor." (PMID 26464442, 2015).
Creutzfeldt-Jakob disease (1 paper, 2016). "Likewise, ND5 and VWA5A have been found to be upregulated in patients with Creutzfeldt-Jakob disease and sheep infected with scrapie, respectively." (PMID 26807844, 2016).
glaucoma (1 paper, 2021). Increased pressure in the eyeball due to obstruction of the outflow of aqueous humor. "Regarding core ECM genes that were significantly altered only in CAβ3 cells, neither VWA5A (FC = 2.67) nor COL13A1 (FC = −1.64) have been found to be associated with glaucoma, although COL13A1 was differentially regulated in response to the steroid triamcinolone in cultured HTM cells." (PMID 34440692, 2021).
tumor (18 papers, 2017 to 2025). "Vwa5a has been shown to be associated with longevity and tumor suppression." (PMID 39752388, 2025). "In addition, it would be intriguing to investigate whether the loss of VWA5A causes tumor cell-intrinsic alterations—i.e." (PMID 38291227, 2024). "Of the 1003 patients in the validation set, 966 (96.3%) samples had available tumor cells on TMA for adequate interpretation of VWA5A IHC results." (PMID 38291227, 2024). "Taken together, these in vitro functional analyses confirmed the tumor suppressive effect of VWA5A on BCs especially regarding invasive and migratory potentials, therefore, supporting our discovery on proteomics-driven biomarker screening." (PMID 38291227, 2024). "Within the genomic loci, VWA5A gene was first cloned in 1997, and the subsequent functional study suggested that VWA5A acts as a tumor suppressor gene, where overexpression of VWA5A in MCF7 cell line resulted in enhanced tumorigenicity." (PMID 38291227, 2024). "In-vitro experiments confirmed tumor suppressive effect of VWA5A on BCs in HR+ and triple-negative BC cell lines." (PMID 38291227, 2024). "The HPA database showed that proteins (CD177, LGALS2, TMC8, and VWA5A) were significantly dysregulated in tumor tissue relative to normal samples." (PMID 37528394, 2023). "The VIT-vWFA domain arrangement of Vwa1 is characteristic of a broad protein family that includes extracellular ITIH heavy chains, a specific intracellular poly ADP-ribose polymerase (PARP4), and the intracellular tumor suppressing VWA5A/BCSC-1." (PMID 37779900, 2023). "When the VWA5A gene is highly expressed, tumor patients make less progress after chemotherapy, suggesting that the upregulation of this gene promote chemotherapy sensitivity." (PMID 34957118, 2021). "Vwa5a, a von Willebrand factor A domain-containing protein, may function as a tumor suppressor outside the cornea." (PMID 40323269, 2025). "In addition to the prognostic significance assessed by METABRIC cohort analysis, the biological influence of VWA5A knock-out confirmed the tumor suppressive role of VWA5A." (PMID 38291227, 2024). "However, consistent consequences of VWA5A knockdown across multiple types of BC cell lines cautiously support the tumor-suppressive nature of the biomarker." (PMID 38291227, 2024). "Autoinhibition or homodimerization might be relevant to the poorly understood tumor suppressor role of the evolutionarily related VWA5A/BCSC-1 in humans." (PMID 37779900, 2023). "The VWA5A plays a role in tumorigenesis as a tumor suppressor." (PMID 36046788, 2022). "VWA5A, also known as breast cancer suppressor candidate-1 (BCSC-1), is investigated as a tumor suppressor gene." (PMID 35269758, 2022).
cancer (4 papers, 2008 to 2024). A tumor composed of atypical neoplastic, often pleomorphic cells that invade other tissues. "Regarding the remaining model genes, like VSTM4 and VWA5A, they have also been reported to have connections with cancer." (PMID 38007443, 2023). "VWA5A gene, also known as BCSC1 or LOH11CR2A, is located within the chromosome 11q23–q24, which has been known to be frequently (ranging from 45 to 63%) deleted in various cancers including breast, ovary, uterine cervix, and lung." (PMID 38291227, 2024).
infection (1 paper, 2023). The state of being infected such as from the introduction of a foreign agent such as serum, vaccine, antigenic substance or organism. "Genes encoding prostatic acid phosphatase (ACPP), MUM1 like 1 (MUM1L1, also known as PWWP3B) and von Willebrand factor A domain containing 5A (VWA5A) represent infection-associated genes whose expression is up-regulated in TashAT2/BoMac." (PMID 37276213, 2023).
VWA5A also shares sentences with these, for which no sentence is quoted: glioma (1 paper); melanoma (1); nasopharyngeal carcinoma (1); scrapie (1); squamous cell carcinoma (1).